TRPM2 (transient receptor potential cation channel subfamily M member 2)
Description:
[Isoform 1]: Nonselective, voltage-independent cation channel that mediates Na(+) and Ca(2+) influx, leading to increased cytoplasmic Ca(2+) levels. Functions as a ligand-gated ion channel, gated by intracellular adenosine diphosphate ribose (ADP-ribose), Ca(2+), warm temperature, and oxidative stress. The precise physiological activators are under debate; the true, physiological activators may be ADP-ribose and ADP-ribose-2'-phosphate. Binding of ADP-ribose to the cytoplasmic Nudix domain causes a conformation change; the channel is primed but still requires Ca(2+) binding to trigger channel opening. Extracellular Ca(2+) passes through the channel and increases channel activity. Contributes to Ca(2+) release from intracellular stores in response to ADP-ribose. Plays a role in numerous processes that involve signaling via intracellular Ca(2+) levels (Probable). Besides, mediates the release of lysosomal Zn(2+) stores in response to reactive oxygen species, leading to increased cytosolic Zn(2+) levels. Plays a role in mediating behavorial and physiological responses to moderate heat and thereby contributes to body temperature homeostasis. Plays a role in insulin secretion, a process that requires increased cytoplasmic Ca(2+) levels (By similarity). Required for normal IFNG and cytokine secretion and normal innate immune immunity in response to bacterial infection. Required for normal phagocytosis and cytokine release by macrophages exposed to zymosan (in vitro). Plays a role in dendritic cell differentiation and maturation, and in dendritic cell chemotaxis via its role in regulating cytoplasmic Ca(2+) levels (By similarity). Plays a role in the regulation of the reorganization of the actin cytoskeleton and filopodia formation in response to reactive oxygen species via its role in increasing cytoplasmic Ca(2+) and Zn(2+) levels. Confers susceptibility to cell death following oxidative stress. [Isoform 2]: Lacks cation channel activity. Does not mediate cation transport in response to oxidative stress or ADP-ribose. [Isoform 3]: Lacks cation channel activity and negatively regulates the channel activity of isoform 1. Negatively regulates susceptibility to cell death in reposponse to oxidative stress.
Synonyms: LTrpC-2; LTrpC2; TrpC7; EREG1; KNP3; NUDT9L1; NUDT9H
Tractability: Small molecule: a structure with a bound ligand is known; a high-quality ligand is known; it belongs to a druggable protein family. Antibody: UniProt places it where antibodies can reach, with high confidence; its Gene Ontology location is reachable by antibodies, with high confidence; UniProt predicts a signal peptide or a membrane-spanning region. PROTAC: ubiquitination databases record sites on it; its protein half-life has been measured; a small molecule that binds it is known.
Target class: Voltage-gated ion channel; Ion channel; Transient receptor potential channel
Gene: Protein-coding gene on chromosome 21 (44,350,072 to 44,445,246, forward strand). Ensembl gene ENSG00000142185.
Subcellular location: Cell membrane; Perikaryon; Cell projection; Cytoplasmic vesicle; Lysosome; Cell membrane (Isoform 1); Cell membrane (Isoform 2); Cell membrane (Isoform 3)
Pathways (Reactome):
Immune System: Neutrophil degranulation
Transport of small molecules: TRP channels
Gene Ontology:
Molecular function: ADP-ribose diphosphatase activity; calcium ion binding; hydrolase activity; intracellularly gated calcium channel activity; ligand-gated calcium channel activity; mono-ADP-D-ribose binding; monoatomic cation channel activity; calcium channel activity; manganese ion transmembrane transporter activity; monoatomic ion channel activity
Biological process: calcium ion transmembrane import into cytosol; calcium ion transmembrane transport; cellular response to calcium ion; cellular response to hydrogen peroxide; protein homotetramerization; regulation of actin cytoskeleton organization; regulation of filopodium assembly; release of sequestered calcium ion into cytosol; response to purine-containing compound; zinc ion transmembrane transport; calcium ion import across plasma membrane; calcium ion transport; cellular response to temperature stimulus; dendritic cell chemotaxis; dendritic cell differentiation; temperature homeostasis; calcium-mediated signaling; manganese ion transmembrane transport; monoatomic ion transport; response to heat; response to oxidative stress; transmembrane transport
Cellular component: lysosome; plasma membrane; cytoplasmic vesicle; cytoplasmic vesicle membrane; ficolin-1-rich granule membrane; lysosomal membrane; perikaryon; specific granule membrane; tertiary granule membrane; membrane
Genetic constraint (gnomAD): Loss-of-function variants: 159 observed, 173.22 expected, observed/expected ratio (o/e) 0.92, 90% interval 0.81 to 1.05. The upper end of that interval is the gene's LOEUF score, 1.05, which puts it in group 4 of 6, group 1 being the genes least tolerant of losing a copy. Missense variants: 2,049 observed, 2,048.5 expected, observed/expected ratio (o/e) 1, 90% interval 0.96 to 1.04. Synonymous variants: 951 observed, 869.07 expected, observed/expected ratio (o/e) 1.09, 90% interval 1.04 to 1.15.
Homologues: Orthologues: macaque TRPM2 (96% identical), chimpanzee TRPM2 (88% identical), mouse Trpm2 (85% identical), rat Trpm2 (85% identical), guinea pig TRPM2 (82% identical), pig TRPM2 (82% identical), dog TRPM2 (81% identical), tropical clawed frog trpm2 (66% identical), zebrafish trpm2 (50% identical), Caenorhabditis elegans trpl-3 (8% identical), Caenorhabditis elegans trpl-2 (8% identical), Caenorhabditis elegans trpl-5 (6% identical). Paralogues in human: TRPM8 (31% identical), TRPM5 (29% identical), TRPM4 (29% identical), TRPM3 (27% identical), TRPM7 (26% identical), TRPM6 (26% identical), TRPM1 (26% identical).
Diseases named in the same sentence as TRPM2 in open-access papers:
TRPM2 is named in the same sentence as 197 diseases in open-access papers, as found by Europe PMC text mining. Sharing a sentence is not in itself a finding about the gene and the disease. The quoted sentences say what the papers report.
neuroblastoma (43 papers, 2015 to 2025). Neuroblastoma (NB) is the most common solid, extracranial childhood tumor. "In the case of both triple-negative as well as estrogen-receptor-positive breast cancer, the inhibition of TRPM2 caused the rise of DNA destruction and cytotoxicity, like neuroblastoma." (PMID 37337283, 2023). "In various cancers including gastric cancers, and neuroblastoma, TRPM2 is known to conserve viability, and several underlying mechanisms of action have been proposed." (PMID 37337283, 2023). "In neuroblastoma, the TRPM2 variant TRPM2-L protected cells from oxidative stress by increasing levels of FOXO3a (a transcription factor) and superoxide dismutase 2, which help reduced the production of reactive oxygen species (ROS) and prevented oxidative cell death." (PMID 40236296, 2025). "High levels of oxidative stress found in TRPM2 deficient neuroblastoma cells may be a potential mechanism to explain the increased DNA damage found in breast cancer when TRPM2 is inhibited." (PMID 40078961, 2025). "Inhibition of TRPM2 could cause tumor cell death, and promote the tumor drug sensitivity in T cell leukemia, gastric cancer, breast cancer cells, and neuroblastoma, to chemotherapeutic agents." (PMID 37608401, 2023). "In neuroblastoma, this group demonstrated that inhibition of TRPM2 triggers cell death and is associated with a decrease in HIF-1/2 and its downstream target BNIP3, leading to the accumulation of Hsp60 and Tom20 proteins, two key indicators of decreased autophagy and mitophagy." (PMID 37576339, 2023). "Treating neuroblastoma cells with MPP+ co-stimulated TRPM2 and NOX2, leading to increased intracellular Ca2+." (PMID 40722879, 2025). "TRPM2 has been shown to regulate autophagy in neuroblastoma, gastric cancer, breast cancer and others through several pathways." (PMID 40078961, 2025). "Research that used CRISPR/Cas9 technology to knock out TRPM2 in SH-SY5Y neuroblastoma cells revealed inhibited cell growth." (PMID 39007141, 2024). "TRPM2 channels and their isoforms coordinate both autophagy and oxidative stress processes in neuroblastoma." (PMID 39633507, 2024). "The ultimate result of TRPM2 inhibition is decreased cell growth and proliferation in several cancers, including breast, prostate, oral, skin, and neuroblastoma." (PMID 37445615, 2023). "For instance, activation of TRPM2 not only enhances cell proliferative ability but also decreases sensitivity to chemotherapy in neuroblastomas." (PMID 37569287, 2023). "TRPM2 exhibited similar results; higher expression of TRPM2 had been proven in various cancers including breast cancer, prostate cancer, pancreatic cancer, leukemia, and neuroblastoma." (PMID 36830651, 2023). "CREB has been reported to be downstream of TRPM2 activation in neuroblastoma cells and in AML cells." (PMID 38390373, 2023). "Because of its roles in proliferation and cell death, TRPM2 has been studied in several cancers, including breast, prostate, oral, neuroblastoma, and melanoma." (PMID 37445615, 2023). "It was reported that TRPM2 sustained cell viability, restore mitochondrial function, reduce reactive oxygen species (ROS) in neuroblastoma, and lead to NLRP3 inflammasome activation." (PMID 37608401, 2023). "In neuroblastoma, the same pathway is activated by TRPM2, along with the transcription factors HIF-1α1, E2F1, FOXM1, and CREB." (PMID 37507867, 2023). "TRPM2 is highly expressed in many human cancers (neuroblastoma, breast, gastric, lung, pancreatic, prostate cancer, squamous cell carcinoma, and T-cell leukemia), where its activation increases malignant cell survival." (PMID 37892239, 2023). "In neuroblastoma, Miller’s group demonstrated that inhibition of TRPM2 increased the cytotoxicity of doxorubicin, a widely used anticancer drug in chemotherapy to treat various cancers." (PMID 37576339, 2023). "Activation of TRPM2 increased the expression of α1, αv, β1, and β5 integrins and, consecutively, migration and invasion of neuroblastoma." (PMID 37507867, 2023).
neuroblastoma (continued). "In neuroblastoma cells where TRPM2 was depleted, tumor development in xenografts considerably declined as well as the sensitivity of doxorubicin increased." (PMID 37337283, 2023). "The roles of Akt and ERK phosphorylation in enhanced migration and invasion mediated by TRPM2 in neuroblastoma were examined here." (PMID 36446940, 2022). "Here, we demonstrate that in neuroblastoma cells highly expressing TRPM2, phosphorylation of both Akt and ERK are increased and inhibitors of Akt and ERK decreased migration and invasion." (PMID 36446940, 2022). "Other studies in cardiac and neuroblastoma cells have shown that Ca2+ entry via TRPM2 activates Pyk2/MCU signalling and modulates mitochondrial function and cell survival." (PMID 35269464, 2022). "Here, neuroblastoma cells with high TRPM2 expression demonstrated increased migration and invasion capability." (PMID 36446940, 2022). "TRPM2 is highly expressed in a number of cancers including breast, lung, pancreas, prostate, neuroblastoma, and leukemia." (PMID 36446940, 2022). "This work demonstrates that high TRPM2 expression in neuroblastoma has a functional role in increasing migration and invasion through enhanced expression of α1, αv, β1, and β5 integrins and integrin complexes." (PMID 36446940, 2022). "WEE1, CHEK1, BRCA1, FANCD2, PARP1, and phosphorylation of CHEK1 and ATR were significantly reduced in TRPM2 deleted neuroblastoma and myeloid leukemia cells after doxorubicin treatment." (PMID 35428820, 2022). "SH-SY5Y neuroblastoma cells in which TRPM2 was deleted with CRISPR technology demonstrated significantly reduced proliferation compared to scrambled control cells, quantitated with trypan blue exclusion or XTT analysis." (PMID 35428820, 2022). "Our analysis compared mRNA levels in SH-SY5Y neuroblastoma cells with TRPM2 deletion (KO) to the same cells stably transfected with TRPM2." (PMID 36446940, 2022). "Treatment of TRPM2-knockout neuroblastoma cells with doxorubicin decreased cell viability, RNAs encoding for transcription factors, E2F1/2 and FOXM1, and cell cycle regulators, including CDK1, Cyclin B1, CKS1, and PLK." (PMID 36844925, 2022). "Numerous studies reported that TRPM2 was widely expressed in various tumor cells including neuroblastoma, gastric cancer, pancreatic cancer, acute myeloid leukemia, and prostate cancer." (PMID 36008839, 2022). "Transient receptor potential melastatin 2 (TRPM2), which is located on plasma membranes, inhibited the effect of the anti-cancer drug doxorubicin in neuroblastoma." (PMID 36555115, 2022). "The role of Akt and ERK in increased migration or invasion of neuroblastoma cells with high TRPM2 levels was examined following treatment with the Akt inhibitor afuresertib or the ERK inhibitor ravoxertinib." (PMID 36446940, 2022). "In SH-SY5Y neuroblastoma cells with increased expression of TRPM2, integrin complexes of α1β1, αvβ1 and αvβ5 were identified." (PMID 36446940, 2022). "Activation of Akt and ERK in cells with high TRPM2 expression also modulates increased neuroblastoma migration and invasion." (PMID 36446940, 2022). "Here, inhibitors of each of the three complexes α1β1, αvβ1, and αvβ5 significantly inhibited the increased migration and invasion in neuroblastoma cells highly expressing TRPM2." (PMID 36446940, 2022). "Our results demonstrate that TRPM2 promotes cell cycle progression, viability, and DNA repair in neuroblastoma and myeloid leukemia after doxorubicin treatment." (PMID 35428820, 2022). "In in vitro and in vivo models of acute myeloid leukemia (AML), TRPM2 showed a mechanism of action similar to that observed in neuroblastoma." (PMID 36844925, 2022). "Here, the role of TRPM2 in migration and invasion of neuroblastoma and the mechanisms were investigated." (PMID 36446940, 2022).
neuroblastoma (continued). "RNA seq showed significantly increased mRNA for integrins α1, α3, α5, α9, αv, and β5 in neuroblastoma cells highly expressing TRPM2, compared to knockout cells transfected with empty vector." (PMID 36446940, 2022). "To identify mechanisms involved in increased migration and invasion of neuroblastoma cells with high TRPM2 expression, we first examined expression of integrin genes." (PMID 36446940, 2022). "Here, the role of TRPM2 in cell survival was examined in neuroblastoma cells with TRPM2 deletion with CRISPR technology." (PMID 35428820, 2022). "Together, the roles of calcium entry thorough TRPM2 in modulating mitochondrial function, bioenergetics, ROS levels, and DNA repair combine to sustain neuroblastoma proliferation and viability, which are significantly impaired in TRPM2 blockade or deletion." (PMID 36446940, 2022). "In neuroblastoma tumor cells and xenograft mice model, TRPM2 modulates both antioxidant response and ROS production, prompting cell survival." (PMID 36844925, 2022). "In our studies, high TRPM2 expression in neuroblastoma cells resulted in increased migration and invasion, essential features of metastatic disease." (PMID 36446940, 2022). "Oz and Celik investigated the actions of curcumin on TRPM2 channels in SH-SY5Y neuroblastoma cells heterologously expressing TRPM2." (PMID 34439491, 2021). "Recent studies have demonstrated that TRPM2 was highly expressed in melanoma, breast cancer, prostate cancer, tongue cancer, neuroblastoma, and kidney cancer." (PMID 35071322, 2021). "Studies with rat hepatocytes and neuroblastoma cells have provided evidence that curcumin inhibits TRPM2 channels." (PMID 34439491, 2021). "TRPM2 channel has been identified as playing an important role in several types of cancers including breast cancer, neuroblastoma, prostate cancer, head and neck cancer, melanoma, and colorectal cancer." (PMID 32423430, 2020). "A similar effect was observed in TRPM2-depleted neuroblastoma cell lines following treatment with doxorubicin." (PMID 32575381, 2020). "In contrast, upregulated TRPM2 is correlated with poor overall survival in patients with neuroblastoma and gastric cancer." (PMID 32575381, 2020). "TRPM2 inhibition reduced neuroblastoma growth and enhanced chemotherapy responsiveness through decreased mitochondrial function and increased ROS21,31." (PMID 32312983, 2020). "Taken together, all studies in neuroblastoma show the critical role of TRPM2 that modulates both ROS production and the antioxidant response through the Ca2+ entry via the channel activation." (PMID 33092205, 2020). "TRPM2 mRNA quantitated in hematopoietic cells was significantly greater than that in neuroblastoma SH-SY5Y cells." (PMID 32312983, 2020). "Full-length and short isoforms of the TRPM2 channels (TRPM2-L and TRPM2-S respectively) are shown to be upregulated in neuroblastoma tissues compared to adrenal glands." (PMID 30691160, 2019). "TRPM2 inhibition in neuroblastoma reduces cell viability through mitochondrial dysfunction, decreased cellular bioenergetics, and increased ROS levels." (PMID 31575956, 2019). "High ROS levels are found in TRPM2 depleted neuroblastoma cells compared to controls, showing that maintenance of GSH and NADPH levels in these cells is critically important in regulating cytotoxicity." (PMID 31575956, 2019). "In neuroblastoma, TRPM2 has been shown to protect cell viability by maintaining mitochondrial function, cellular bioenergetics, autophagy and reducing ROS levels." (PMID 31575956, 2019). "Many cancers including neuroblastoma express high levels of TRPM2, which preserves cell viability by maintaining mitochondrial function, cellular bioenergetics, and modulating ROS20–23,52." (PMID 31575956, 2019). "Inhibition of TRPM2 function in neuroblastoma reduces cell viability after doxorubicin and Pyk2 and CREB activation." (PMID 30020827, 2018).